SOX2 (SRY-box transcription factor 2)
Diseases named in the same sentence as SOX2 in open-access papers (continued):
Sharing a sentence is not in itself a finding about the gene and the disease.
cancer (continued). "Thus, it is unclear if the associations between NOTCH1 and expression of ALDH3A1 and SOX2 represent a genuine shift toward a cancer stem cell phenotype, or instead signify the transition to early differentiated progenitors (i.e., transiently amplifying cells)." (PMID 33322834, 2020). "SOX2 (sex-determining region-Y homeobox-2) is a transcription factor essential for the maintenance of pluripotency and is also associated with stem-cell-like properties in preclinical cancer models." (PMID 32365581, 2020). "SOX2, a pluripotency-associated transcription factor, is an emerging biomarker for the prediction of prognosis and therapeutic targets for cancer treatment because it plays an important role in the development and maintenance of the stem cell state and is associated with cancer progression." (PMID 33182283, 2020). "On this basis, we could speculate that the increased cancer risk in patients harboring SOX2-expressing lesions may reflect the presence of a larger proportion of cells presenting cancer stem-like properties." (PMID 30823625, 2019). "Moreover, we observed that FAM83F overexpression induced the reactivation of stem cell markers such as Sox2, Nanog and Lin28b usually associated cancer stem cells and undifferentiated thyroid cancer." (PMID 30881348, 2019). "Interestingly, SOX2, a key regulator in the plasticity of cancer stemness, was also closely associated with poor prognosis in TSCC patients." (PMID 31552166, 2019). "Hence, immunohistochemical evaluation of SOX2 is proposed to be incorporated into the clinical practice as a complementary and relatively simple molecular test for cancer risk assessment and decision-making." (PMID 30823625, 2019). "Notably, SOX2 also plays a similar role in the context of tumors, where it has been linked to maintenance and self-renewal of cancer stem cells." (PMID 30723235, 2019). "As we have shown that phosphorylation of Sox2 at threonine 116 is directly linked to Sox2 function, screening of BC for pSox2T116 staining may have significant implications for cancer treatment." (PMID 29401647, 2018). "SOX2 has been implicated in growth, tumorigenicity, drug resistance, and metastasis in at least 25 different cancers, TARDBP is involved in apoptosis and cell division, while GFI1B positively regulates c-Myc expression and increases the proliferation rate of cancer cells." (PMID 29950180, 2018). "For some cancers only a single miR has been implicated thus far in the regulation of SOX2." (PMID 28388544, 2017). "Notably, CHD7 physically interacted with SRY‐box 2 (SOX2) transcriptional factor and regulated a set of common target genes associated with cancer and developmental disorders." (PMID 28649742, 2017). "It has been reported that self-renewal, proliferation and differentiation regulated by Nanog/Sox2/Oct4 are the hallmark of stem cell properties that allow CSCs to produce both new cancer stem cells and phenotypically diverse cancer cells with different proliferative potential." (PMID 28837080, 2017). "Proteins such as Sox2, Nanog, and Oct4 are now thought to serve not only as biomarkers tumor stage and therapy response in cancer but also may be directly implicated in the process of carcinogenesis." (PMID 28805675, 2017). "Thus, in addition to its angiogenic action, VEGFA upregulates Sox2 to drive stem cell expansion, together with miR-452 loss and Slug upregulation, providing a novel mechanism whereby cancer stem cells acquire metastatic potential." (PMID 28504716, 2017). "Altogether, the overlapped expression of SOX2OT with SOX2, and the conserved association between them in different developmental systems of vertebrates, and also in human cancer and stem cells all support the existence of a complex functional regulatory relationship." (PMID 26136768, 2015). "The observed anti-cancer effects were confirmed as a result of SOX2 loss." (PMID 26580604, 2015).
cancer (continued). "Since SOX2 is associated with gastric differentiation we studied whether this was maintained in cancer, using MUC5AC as a gastric marker." (PMID 25300947, 2014). "Sox2 was bound to stem cell- and cancer-associated genes in RR cells." (PMID 25380620, 2014). "To further support the concept that Sox2 contributes to tumorigenesis and stemness in BC by upregulating these stem cell- or cancer cell-associated genes, we examined the oncogenic effects of Mucin-15 (Muc15), which has not been previously shown to be a Sox2 downstream target." (PMID 25380620, 2014). "Aside from developmental diseases, accruing research has strongly associated SOX2 with cancer." (PMID 25114775, 2014). "We believe that our finding of Sox2 regulating an array of cancer- and stem cell-associated genes provides a mechanistic explanation as to how Sox2 enhances stemness and tumorigenesis in cancer cell subsets." (PMID 25380620, 2014). "Additionally, a high SOX2 expression level in primary cancer cells was also associated with LN metastasis, which differs from ALDH1 and CD204(+) macrophages in this respect." (PMID 24376714, 2013). "However, dysregulation of SOX2 expression has been implicated in a spectrum of cancers." (PMID 40034124, 2025). "Moreover, SOX2 is a known pluripotency-associated SC TF linked to a multitude of cancer types and cancer cell traits such as proliferation, migration, resistance to established cancer therapies and expression in CSCs." (PMID 39478150, 2024). "Interestingly, SOX2 has also been observed in association with changes in cancer cell metabolism such as enhanced oxidative phosphorylation, glycolysis and fatty acid metabolism, along with increased mitochondrial quantity, which is thought to contribute to the cells’ ability to metastasize." (PMID 36980876, 2023). "Moreover, SOX2 is implicated in the metastasis and tumorigenesis of cancers." (PMID 35711895, 2022). "In ovarian cancer, as a transcription factor, Sox2 directly binds to the promoter of ST6Gal-I to drive transcription and increases in N-glycosylated protein α2-6 linked sialic acid, promotes ST6Gal-I and α2-6-linked sialic acid expression, regulates glucose metabolism in cancer cells." (PMID 35022030, 2022). "Indeed, they observed that SOX2, a marker for neural stem cells implicated in the maintenance of cancer stem cells and therapeutic resistance of cancer cells, was observed only when endothelial and glioblastoma cells were grown compartmentalized and not when they are mixed." (PMID 35049737, 2022). "However, whether higher SOX2 expression is a favorable or unfavorable risk factor depends on the primary organ of cancer." (PMID 33182283, 2020). "Moreover, overexpression of SOX2 is often associated with increased cancer aggressiveness, resistance to chemoradiation therapy and decreased survival rate, which has been reported in various cancer types, including TSCC." (PMID 31552166, 2019). "CD133 and SOX2 might be associated with worse prognosis in advanced cancer." (PMID 30693028, 2019). "Moreover, ectopic expression and amplification of SOX2 are associated with cancer development." (PMID 29374236, 2018). "Further analysis of exosomal DNA sequences of NANOG and other embryonic stemness genes (OCT3/4, SOX2, etc.)may establish a robust collection of exosome based diagnostic markers, and further elucidate the mechanisms of cancer formation, progression, and metastasis." (PMID 29787607, 2018). "To determine whether cancer cell phenotypes associated with miR-371-5p expression could be reversed via restoration of SOX2, we transfected miR-371-5p-depleting cells with shRNAs toward SOX2 in HCT116 and SW480 cells." (PMID 25868860, 2015). "For example, the four transcription factors commonly utilized in iPSC reprogramming Sox2, Oct4, Nanog, and Klf4 have been linked to carcinogenesis, increased cancer malignancy and tumor drug resistance and are overexpressed in many cancers and cancer stem cells." (PMID 22919402, 2012).
cancer (continued). "SOX2/SOX9 enable natural killer cell evasion by downregulating major histocompatibility complex class I markers in cancer cells." (PMID 41268614, 2026). "Cancer stem cells preferentially expressed the signaling molecule FAM3C induced by the stem cell transcription factor SOX2 to drive expression of proline synthesis enzymes." (PMID 42222882, 2026). "Patients with SOX2-positive tumors exhibited significantly worse overall survival (OS), cancer-specific survival (CSS) and recurrence-free survival (RFS; P=0.004, P=0.005 and P=0.011, respectively) during a median follow-up period of 39.3 months." (PMID 42137465, 2026). "The intermediate filament Nestin and the stem cell (SC)-transcription factor SOX2 have been shown to play a role in the maintenance of CSC features in different cancer entities." (PMID 41129070, 2026). "Although not much is currently known regarding the specific functions of most of these lncRNAs, MAP3K20-AS1, STARD4-AS1 and PCAT1 are high-risk factors for different cancers and PCAT1 also is known to activate SOX2 as well as affect cGAS/STING signaling." (PMID 40018706, 2025). "TFs like MYC and SOX2, vital for cellular reprogramming, also drive oncogenic transformation, underscoring their role in cancer’s aggressive traits." (PMID 40016470, 2025). "We examined the effect of PCA as an Akt/Sox2 signaling inhibitor in targeting breast CSCs in 4T1 cancer cells." (PMID 40076435, 2025). "Cancer stem cells maintain stemness by regulating pluripotency genes, including Nanog, Sox2, and Bmi1, in response to Hh ligands secreted by neighboring stromal cells." (PMID 39352634, 2025). "BMPs promote anoikis and inhibit metastasis by downregulating SOX2, while TGF-β/activin enhances cancer cell survival and metastasis via SOX2 upregulation." (PMID 40024947, 2025). "In this study, we investigated the role of PP1γ in the progression of ESCC and its modulation of YAP1 and cancer stem cell markers such as SOX2." (PMID 40626009, 2025). "Numerous cancer types have been shown to have SOX2 as an oncogenic driver that is enhanced during carcinogenesis, metastasis, and recurrence." (PMID 40777043, 2025). "Among the YTHDC2 associated and cancer-related genes (CRGs), CHD1 regulates WNT signaling, EMT and pluripotency genes like SOX2 and NANOG." (PMID 41145440, 2025). "Single-cell mapping revealed complex interactions between cancer subpopulations and specific genes, showing significant alterations in the proportions of CXCL1 and SOX2 cancer subpopulations." (PMID 40568194, 2025). "Cancer stemness is recognized by the presence of stemness-related markers in human cancers such as Oct4, Sox2, Klf4, c-Myc, Sall4, and Nanog." (PMID 40076435, 2025). "Upon uptake of these EVs, β-catenin enters the nucleus of recipient cancer cells and enhances the expression of cancer stemness factors including c-Myc, SOX2, and OCT4." (PMID 40657369, 2025). "This study introduces a safe and effective intratumoral EGFR‐targeted CRISPR‐LNP delivery strategy for knocking out SOX2, which is a cancer‐specific gene." (PMID 39736115, 2025). "The biological activity of cancer stem cells (CSCs) is governed by essential stemness factors, such as Sox2 and c-Myc, which are pivotal for preserving stem cell characteristics and facilitating cellular proliferation." (PMID 40332113, 2025). "After culturing in stem cell medium, the expression of cancer stem cell markers such as Nanog, Sox2, Nestin, and oligodendrocyte transcription factor 2 (Olig2) in GSC spheres was confirmed by immunostaining." (PMID 39721005, 2025).
cancer (continued). "Evidence suggests that the transcription factor SOX2 exerts a positive effect on cancer cell activities, including proliferation, invasion, migration, EMT, as well as spheroid and colony formation." (PMID 39976818, 2025). "Knockdown of SOX2 in human CRC cells has been reported to impair cancer cell stemness, in vitro cell migration and invasion, and metastasis in a mouse model." (PMID 40179020, 2025). "The transcription factor SOX2 is integral to embryonic development, and its dysfunction can lead to a variety of functional disorders or the onset of cancer." (PMID 39976818, 2025). "In AR inhibitor-resistant cells, H3K27ac enrichment at TWIST1 enhancers sustains mesenchymal traits, while dynamic H3K4me3 modifications at stemness-related genes (SOX2) couple EMT with cancer stem cell properties." (PMID 40519259, 2025). "The role of SOX transcription factors and the effect of their dysregulation on cancer progression and on therapy response is not fully understood and some data investigating the impact of SOX2 and SOX9 in OSCC remain controversial." (PMID 39180200, 2025). "EMT pathway gene expression changes were prominent in human CRCs with low SOX9 expression and in a mouse cancer model with high SOX2 expression." (PMID 40179020, 2025). "ID2 induces the expression of nanog homeobox (NANOG) and sry‐box transcription factor 2 (SOX2), which are cancer stem cell markers, through the PI3K/AKT pathway, and contributes to cell proliferation and cancer stem cell maintenance." (PMID 40448344, 2025). "Nonetheless, the regulatory mechanisms that control SOX2 activity in cancer remain incompletely understood." (PMID 40674376, 2025). "By working in tandem with SOX2, the Wnt/β-catenin pathway plays a vital role in maintaining cancer stemness." (PMID 40777043, 2025). "Cancer stem cells (CSCs) have been described as a small subpopulation of cells within the tumor with self-renewal and pluripotency (via Oct4, Nanog, Sox2), resistance to radiation and chemotherapy, EMT profile, and high possibility for cancer potential." (PMID 41303402, 2025). "Numerous studies have demonstrated that SOX2 exerts a positive influence on cancer cell properties, including proliferation, migration, invasion, and metastasis." (PMID 40034124, 2025). "SOX2, PIWI proteins, and MALAT1 are molecular regulators implicated in cancer progression, proliferation, and epithelial-mesenchmal transition (EMT)." (PMID 40674376, 2025). "Both OCT4 and SOX2 are master pluripotent factors serving as a molecular switch that drives the fate of CSCs during cancer progression, with proven clinical potential." (PMID 41463190, 2025). "This review will focus on exploring the mechanisms of SOX2 in PCa, examining its potential roles in cancer initiation, progression, metastasis, and resistance." (PMID 40821114, 2025). "Sox2, c-Myc, Klf4, and Oct4 are four core stemness factors that play pivotal roles in maintaining cancer cell stemness." (PMID 40332113, 2025). "For example, SRY-box transcription factor 2 (SOX2) promotes chemoresistance, cancer stem cell properties, and epithelial-mesenchymal transition in CRC." (PMID 41331125, 2025). "Multiple studies have revealed the molecular regulatory mechanisms of SOX2 in various cancers, but our understanding of its specific role in PCa progression remains limited." (PMID 40821114, 2025). "SOX2 is not only frequently over-expressed across various cancer types, but it also modulates the physiological functions of cancer cells through complex protein–protein interactions and cellular signaling pathways." (PMID 39976818, 2025). "Despite the significant therapeutic potential of directly or indirectly targeting SOX2 in cancer treatment, it is important to note that SOX2 also plays critical roles in normal physiological processes." (PMID 40821114, 2025).
cancer (continued). "In this study, we delved into the mechanisms underlying drug resistance in SCLC, identifying the pivotal role of the PRMT1/SOX2 axis in governing cancer stemness, a factor that substantially contributes to SCLC chemoresistance." (PMID 41377018, 2025). "SOX2 is a transcriptional factor for cancer stemness, whose transcriptional expression is promoted by the accumulated FOXO1, which in turn, stimulates FOXO1 transcription and shapes a positive regulatory loop." (PMID 40746611, 2025). "As a marker of cancer progenitor cells, the overexpression of SOX2 demonstrates increased BRAF inhibitor resistance." (PMID 39944829, 2025). "A novel LIFR inhibitor, EC359, resulted in the induction of apoptosis and reduced the levels of cancer stem cell markers SOX2, OCT4, and NANOG in EC." (PMID 40804837, 2025). "The mounting evidence further suggests that SOX2 operates as a factor bestowing resistance to conventional cancer therapies while maintaining a presence within CSCs." (PMID 40034124, 2025). "Cancer stem-like cells phenotype is regulated by a set of CSC-associated transcription factors including c-Myc, OCT4, SOX2 and NANOG which are known to drive cancer progression." (PMID 40136647, 2025). "ALDOA lactylation at the K230 and K322 sites causes DDX17 release from ALDOA, allowing DDX17 entry into the nucleus and binding to SRY-box transcription factor 2 (SOX2) to activate their target genes to maintain cancer cell stemness." (PMID 40333742, 2025). "TAM produce IL‐10 which improves the viability of cancer cells in NSCLC by stimulating the JAK1/STAT1/NF‐κB/Notch1 signaling pathway and promoting the expression of SOX‐2 and other genes linked to cancer cells." (PMID 39927632, 2025). "The upregulated ABCB1, ZEB1, and CD44 were engaged in microRNA regulation in cancer, SOX2 and KLF4 were engaged in pluripotency of stem cells, and TWIST1 and CD44 contributed to proteoglycans in cancer." (PMID 40251609, 2025). "MTA3 negatively regulates SOX2, a key transcription factor involved in cancer stem cell maintenance, thereby suppressing the stem-like properties and proliferative capacity of tumor cells." (PMID 41584603, 2025). "Ultimately, this highly specific treatment strategy that includes cancer‐specific target gene SOX2 with functional anti‐EGFR tLNPs holds great promise for safe and efficient CRISPR treatment HNC, and ultimately for many other palpable solid cancers." (PMID 39736115, 2025). "In this study, we developed an effective method for IT injection of EGFR‐targeted CRISPR LNPs (cLNPs) that knock out a cancer‐specific gene, SOX2." (PMID 39736115, 2025). "Supporting a role of glutaminolysis in DEHP‐induced cancer stemness, glutamine deprivation produced a markedly greater reduction in sphere formation and SOX2 expression in DEHP‐treated MCF7 cells than in parental cells." (PMID 40959920, 2025). "Our previous results demonstrated that TAB2 promotes cancer stemness through NF‐κB pathway activation, as evidenced by enhanced sphere formation capacity and increased expression of stem cell markers SOX2 and BMI1." (PMID 40133221, 2025). "Since its identification as a key regulator of stem cell properties, SOX2 has been shown to be overexpressed in at least 25 types of human cancer, driving tumorigenesis through increased cell proliferation, migration, invasion, and metastasis." (PMID 40674376, 2025). "In these high-grade lesions, SOX2 protein is typically located in cancer cell clusters at the expanding or invasive front, where these cells are predominantly chromogranin-A-positive." (PMID 40821114, 2025). "Research suggests that reduced levels of SOX2 can impede the growth and invasion of cancer cells while promoting their re-differentiation." (PMID 39976818, 2025). "We observed that manipulation of DUSP9 expression led to corresponding changes in the expression of core cancer stemness genes, including SOX2, NANOG and OCT4." (PMID 41383134, 2025).